CDH5 (cadherin 5)
Diseases named in the same sentence as CDH5 in open-access papers (continued):
Sharing a sentence is not in itself a finding about the gene and the disease.
memory impairment (1 paper, 2022). "To inspect the molecular mechanism that contributes to memory impairment, we performed digital gene expression by whole‐genome RNA sequencing and genomics analysis on hippocampal tissue samples obtained from Cdh5‐CreERT2;CDK5f/f and CDK5f/f mice." (PMID 35770064, 2022). "Notably, we found that valproate (VPA) and phenytoin (PHT) augment mRNA expression and protein levels of synapse‐related genes and ameliorate memory impairment in Cdh5‐CreERT2;CDK5f/f mice." (PMID 35770064, 2022).
mitral valve disease (1 paper, 2021). "In fact, VE-cadherin gene expression and immunohistochemical staining was evaluated in canine myxomatous mitral valve disease to investigate the role of EMT in chronic valvulopathies, showing a significant cdh5 gene dysregulation." (PMID 34631854, 2021).
myeloid neoplasm (1 paper, 2020). Proliferation of myeloid cells originating from a primitive stem cell. "The myeloid-biased output of HSCs observed in CDH5-MAPK mice illustrates the impact of chronic vascular inflammation on HSC function and highlights the potential of sustained niche-driven inflammation to influence aging-associated HSC phenotypes including predisposition towards myeloid neoplasms." (PMID 32015345, 2020).
Osteopenia (1 paper, 2020). Osteopenia is a term to define bone density that is not normal but also not as low as osteoporosis. "Since SCGF has been shown to promote osteogenesis, it is likely that the decrease in plasma SCGF levels along with the BM inflammation observed in CDH5-MAPK mice could result in osteopenia." (PMID 32015345, 2020).
pancreatic neuroendocrine tumor (1 paper, 2020). Pancreatic endocrine tumor, also known as pancreatic neuroendocrine tumor (PNET), describes a group of endocrine tumors originating in the pancreas that are usually indolent and benign, but may have the potential to be malignant. "TTR and HP bound to fucose have been already proposed as a biomarkers of PDA; CDH5 in pancreatic neuroendocrine tumors developed in Von Hippel–Lindau disease patients and FCGBP in mucinous cysts in the pancreas and PDA." (PMID 32245227, 2020).
Pancytopenia (1 paper, 2024). An abnormal reduction in numbers of all blood cell types (red blood cells, white blood cells, and platelets). "Arteriole-specific Cx40-MAPK mice developed a robust peripheral pancytopenia that phenocopied the previously observed dysfunction in Cdh5-MAPK mice, including a loss in white blood cells (WBCs), RBCs, and platelets." (PMID 38438768, 2024). "Because pancytopenia is indicative of impaired HSC function in Cdh5-MAPK mice, we examined HSPC parameters in R3-MAPK and Cx40-MAPK models." (PMID 38438768, 2024).
renal clear cell carcinoma (1 paper, 2024). "Knockdown of CDH5 inhibited the proliferation and migration of renal clear cell carcinoma." (PMID 38580922, 2024). "Finally, the function of CDH5 was explored in renal clear cell carcinoma cells." (PMID 38580922, 2024). "In addition, we identified natural small molecule drugs that can target vasculogenic mimicry-related core target proteins by molecular docking, and finally, we verified that CDH5 promotes the proliferation and invasion of renal clear cell carcinoma by in vitro experiments." (PMID 38580922, 2024).
renal dysfunction (1 paper, 2025). "Notably, patients with CKD or renal dysfunction display changes in corresponding genes, such as a loss of the endothelial marker CDH5, an increase in ANGPT2 and PDGFB, and a reduction in ANGPT1." (PMID 40952790, 2025).
sarcoidosis (1 paper, 2016). Sarcoidosis is a multisystemic disorder of unknown cause characterized by the formation of immune granulomas in involved organs. "Several proteins were identified with higher abundance in BAL of sarcoidosis patients, including cadherin 5 (CDH5), transferrin (TF), C-C motif chemokine 24 (CCL24), interleukin 15 (IL15) apolipoprotein A (LPA) and mitochondrial superoxide dismutase (SOD2)." (PMID 27259755, 2016). "As sarcoidosis is considered to be a Th1-driven disease characterized by an accumulation of lymphocytes in BAL fluid, CDH5 levels as a measure of lymphocyte infiltration could potentially be used to monitor disease progression." (PMID 27259755, 2016).
urothelial carcinoma (1 paper, 2023). A malignant neoplasm derived from the transitional epithelium of the urinary tract (urinary bladder, ureter, urethra, or renal pelvis). "However, our research verified that CDH5 was downregulated in urothelial carcinoma tissues and cell lines." (PMID 37809080, 2023).
tumor (442 papers, 2006 to 2026). "Previous studies demonstrated that a high CDH5 expression is mainly associated with tumor angiogenesis." (PMID 37809080, 2023). "The associations between CDH5 and the tumor immune response including immune cells infiltration, immunomodulators expression and chemokines expression were also analyzed." (PMID 37809080, 2023). "In summary, CDH5 was positively associated with a favorable prognosis and effective immune response in tumors, showing a great potential to serve as a novel tumor biomarker and immune checkpoint." (PMID 37809080, 2023). "CDH5 was positively associated with tumor immunity and showed great potential to act as an immune checkpoint for cancer immunotherapy." (PMID 37809080, 2023). "Although vasculature emerged affected in ADAMTS1-deficient tumors, the most relevant action implied the downregulation of endothelial CDH5 in tumor cells, in association with stemness markers." (PMID 32230715, 2020). "The analysis of WT tumors allowed the identification of a cell surface pattern for CDH5, noticeably associated with tumor cells in the vicinity of EMCN-positive vascular niches." (PMID 32230715, 2020). "We further confirmed the up-regulation of Notch3 mRNA in purified tumour-associated endothelial cells from subcutanous injected LLC1 in Cdh5:CreERT2xTomato mice allowing FACS sorting of tumour-associated endothelial cells." (PMID 28719575, 2017). "Moreover, we also found that a low expression of CDH5 was associated with more advanced tumor stage and poorer prognosis of BCa." (PMID 37809080, 2023). "In summary, our results confirmed that CDH5 was closely associated with tumor immune response, and that it could be used as a new immune checkpoint for immunotherapy in the future." (PMID 37809080, 2023). "Importantly,a recent study showed that aberrant extravascular expression of CDH5 has been observed in certain cancer types associatedwith vasculogenic mimicry, which is a blood supply system separatefrom endothelial vessels within tumor cells." (PMID 38739686, 2024). "Monomeric vascular endothelial cadherin (VE-cadherin or cadherin 5) is expressed on tumour neovasculature and progenitor endothelial cells and represents another promising target for altering the vascular microenvironment of GB 92,93." (PMID 40303349, 2025). "The mesenchymal markers SNAIL, SLUG, TWIST, and ZEB1 were upregulated in OX40+ tumor ECs, whereas the adhesion molecules CDH1 (encoding E-cadherin) and CDH5 (encoding VE-cadherin) were downregulated." (PMID 40026246, 2025). "The results of IHC staining analysis confirmed that tumor cell-derived exosomes promoted VM formation by upregulating CDH-5 expression and promoted M2 polarization of TAMs." (PMID 40665298, 2025). "The expression of CDH5 was compared in different tumor types, and CDH5 showed a high expression level in KIRC, THCA, and TGCT and a low expression in LAML, CESC, and KIRP." (PMID 37809080, 2023). "In order to investigate the role of CDH5 in tumor prognosis, we conducted prognosis correlation analyses including OS, DFS, DSS, and PFS in pan-cancer." (PMID 37809080, 2023). "Nevertheless, Flvcr1a;Cdh5-CreERT2 and control mice had comparable tumor vessel density, as indicated by the quantification of vessels number and of the vascular volume of perfused vessels measured by DCE-MRI (respectively)." (PMID 36631598, 2023). "The aberrant expression of CDH5 in a variety of tumor tissues has been verified by bioinformatics analysis and experiments, and the results confirmed that high-expressed CDH5 was positively correlated with worse survival and higher tumor stage." (PMID 37809080, 2023). "LLC xenografts were dissected after 14 days when tumor burden was mostly comparable between Flvcr1a;Cdh5-CreERT2 and control mice, and the tumor vasculature was analyzed on histological sections following staining with the endothelial cell marker CD31." (PMID 36631598, 2023).
tumor (continued). "KEGG-GSEA and Hallmarks-GSEA analyses results indicated that CDH5 was positively related to immune response in most tumor types." (PMID 37809080, 2023). "In our study, CDH5 was found to be positively correlated with immune cell scores in 25 tumor tissues, including BCa." (PMID 37809080, 2023). "The tumor cell killing ability of CD8+ T cells was promoted after co-culturing with CDH5 overexpressed T24 cells." (PMID 37809080, 2023). "In accordance with the presence of enlarged blood vessels, the average vessel perimeter was increased in Flvcr1a;Cdh5-CreERT2 tumor." (PMID 36631598, 2023). "In particular, vessels distribution was different in Flvcr1a;Cdh5-CreERT2 tumor, with a lower number of small capillaries and a higher number of larger ones." (PMID 36631598, 2023). "Taken together, CDH5 was differentially expressed in many tumors and was significantly correlated to tumor prognosis." (PMID 37809080, 2023). "Conversely, Flvcr1a;Cdh5-CreERT2 tumor blood vessels displayed a significantly larger average size compared to blood vessel in control tumors, thus explaining the increase in the vascular area." (PMID 36631598, 2023). "Multiple studies demonstrated that cell junction proteins, such as TJP1 and CDH5, regulated tumor angiogenesis to promote tumor invasion and metastasis." (PMID 35173549, 2022). "To quantitatively measure in vivo vascular-like conversion, we generated xenografts with tumor cells transduced with VE-CADHERIN (CDH5-mC) and DESMIN (DES-mC) reporters." (PMID 36261421, 2022). "Mice lacking homophilic Flrt2 binding specifically in endothelial cells (Cdh5-CreERT2+Flrt2flox/R186N+D188T; referred to hereafter as Flrt2iΔEC/ΔFF mice) showed suppression of tumor growth, angiogenesis, and hemorrhaging, similar to those in Flrt2iΔEC mice." (PMID 35104247, 2022). "While expression of the tight-junction gene CLDN5 was similar in Pe1 ECs and Co1 ECs, some adherens junction mRNAs, including VE-cadherin (encoded by CDH5) and CD31, were upregulated in ECs in the tumor core compared with peripheral ECs." (PMID 34228647, 2021). "Many studies have proved that the high expression of Notch4 and CDH5 is an important factor to promote tumor development." (PMID 34149795, 2021). "CDH5 is an adhesion molecule and member of the selectin family that contributes significantly to tumorigenesis and tumor progression." (PMID 33461176, 2021). "E0771.lmb tumor cells were orthotopically injected into wild type mice (Cdh5-CreERt2) or mice with the Shb gene conditionally deleted in EC (Shbflox/flox/Cdh5-CreERt2)." (PMID 34768912, 2021). "Notable genes include KRT80 and CDH5 25, 26, which are suspected to function as tumor promoters in human cancers and are highly expressed in PDAC." (PMID 33390837, 2021). "For certain genes (Il10, Csf3, Cxcl1, Ccl2, Gata3, Il5, and Il13), there was a clear difference between the EC and HC Shb KO effects using Cdh5-CreERt2 or Vav1-Cre tumor-bearing mice, indicating that these effects reflect EC cell autonomy of Shb gene deletion." (PMID 34768912, 2021). "The contribution of CDH5 in the VM phenomenon has already been reported, so we were interested in visualizing human CDH5 in our tumor histological sections by IF." (PMID 32230715, 2020). "Given the strong impairment of ATS1-KO cells to form spheres, we evaluated gene expression levels of NANOG and CDH5 in their primary spheres, according to their alteration in our tumor model." (PMID 32230715, 2020). "Cdh5-CreERRainbow mice were injected with a low dose (0.3 mg) of tamoxifen at D3 post B16-F0 tumor inoculation." (PMID 30604758, 2019).
tumor (continued). "High CDH5 expression correlates with tumor progression, metastasis and poor survival in patients with differentiated-type gastric cancer." (PMID 31324051, 2019). "From the six signature proteins (HLA-A, CFH, CD44, PTPRJ, HP, and CDH5), only CD44 has been previously associated with CRC prognosis in tumor specimens from 74 patients that were assayed by immunohistochemistry." (PMID 26253080, 2015). "To determine the requirement for endothelial FN in tumor growth, we used Cdh5-CreER to excise FN in the endothelium one-week prior to transplant of Lewis Lung tumor cells." (PMID 25807551, 2015). "Genes relatively overexpressed in low-percentage tumours included established stromal-related genes (for example, Collagen (type XV, alpha-1) and Cadherin 5 (type 2, VE-cadherin))." (PMID 16790077, 2006). "For in vivo analysis, we crossed Twist1fl/fl mice with Cdh5-Cre mice to generate an EC-specific Twist1 knockout mouse line, Cdh5-CreERT2;Twist1fl/fl, and used this line to investigate the role of endothelial Twist1 for tumor immunity regulation." (PMID 38416830, 2024). "VE-cadherin (cadherin-5, CD144) is an adherence junction protein ensuring proper barrier function and primarily mediates the paracellular route of leukocyte transmigration and tumor cell metastasis by forming cell-cell junction gaps." (PMID 38726320, 2024). "In glioma and melanoma, CDH5 stimulated tumor progression through inducing vascular formation." (PMID 37809080, 2023). "However, the regulatory role of CDH5 in tumor immune escape and local immune response is rarely studied." (PMID 37809080, 2023). "Thus, to determine the specific role of Dnmt1 in the vasculature during tumor growth and immune surveillance, we generated a conditional deletion model to ablate Dnmt1 in Cdh5+ ECs (Dnmt1iECKO mice)." (PMID 37055433, 2023). "CDH5 was significantly correlated with tumor stage in 6 types of tumors." (PMID 37809080, 2023). "Previous study reported abnormal expression of CDH5 in different tumors, and that CDH5 could regulate tumor development by influencing angiogenesis." (PMID 37809080, 2023). "The current pan-cancer analysis was performed to better understand the role of CDH5 in tumor." (PMID 37809080, 2023). "The expression of CDH5 is abnormal in tumor cells, which may have great potential to serve as a new immune checkpoint." (PMID 37809080, 2023). "Notably, tumor vessel permeability was significantly enhanced in Flvcr1a;Cdh5-CreERT2 mice compared to controls, as indicated by the quantitative analysis of ktrans and kep parameters." (PMID 36631598, 2023). "This suggested that the CDH5 may affect the response of patients to ICIs therapy through influencing tumor immune response." (PMID 37809080, 2023). "miR-939 increased tumor cell trans-endothelial migration and regulated CDH5 in endothelial cells." (PMID 34707990, 2021). "To specifically determine if the loss of cIAP1 in the endothelium was the critical compartment for the reduction of tumor colonies in the lungs, we crossed ciap1fl/fl mice with a tamoxifen inducible Cre line driven by the Cdh5 (VE-cadherin) promoter (ciap1VEC)." (PMID 33546280, 2021). "Interestingly, ADAMTS1 and CDH5 also appeared significantly induced in the tumor context, suggesting again their direct link during tumor progression." (PMID 32230715, 2020). "A combination of experimental in vitro and in vivo approaches, together with the use of bioinformatics methodologies on public tumor databases, allowed us to unveil the unexplored relevance of endothelial-specific molecules, such as CDH5, strongly correlating with ADAMTS proteases." (PMID 32230715, 2020).